PPARG (peroxisome proliferator activated receptor gamma)
Diseases named in the same sentence as PPARG in open-access papers (continued):
Sharing a sentence is not in itself a finding about the gene and the disease.
lung carcinoma (continued). "Both reduced (PPARγ) expression and elevated COX-2 within the tumor are associated with poor prognosis in lung cancer patients, and recent work has indicated that these signaling pathways may be interrelated." (PMID 18769553, 2008). "This approach may provide an important new opportunity in learninghow to more effectively exploit the effects of inhibiting LOX and COX pathways,in combination with PPARγ activation, on control of proliferationand apoptosis in lung cancer." (PMID 19277204, 2008). "Exploring the potential ofthese new agents, together with a more comprehensive mechanistic model of the PPARγ function, may provide a solidfoundation for a better design of novel combination therapies for lung cancer." (PMID 19277204, 2008). "Therefore, we hypothesized that ROB may exert an inhibitory effect on lung cancer by activating the PPARγ/PTEN/Akt signaling pathway." (PMID 39450260, 2024). "Thus, PPARγ holds great potential as a therapeutic target for tackling lung cancer." (PMID 38397426, 2024). "Similarly, more recent works demonstrated that metabolites of the flavonoid quercetin suppressed MMP-2 activity and invasion of a lung cancer cell line in a PPARγ-dependent manner, and that PPARγ blocked the increase in activities of MMP-2 and MMP-9 due to Toxoplasma Gondii infection in astrocytes." (PMID 34445581, 2021). "Notably, a recent study found that PPAR response elements (PPRE) existed in the promoter of ALDH1A3, and ALDH1A3 could up-regulate PPARγ in lung cancer cells, consistent with our observation in PDAC cells." (PMID 32612951, 2020). "Thus, our results indicate that programming macrophages with UV-irradiated apoptotic lung cancer cells might create a tumor microenvironment that antagonizes cancer progression and lung metastasis via prolonged PPARγ/PTEN signaling in both TAM and tumor cells." (PMID 30842627, 2019). "Studies conducted on PPARγ agonist or with PPARγ overexpressing cells, support the idea that PPARγ activation is useful to counteract tumor progression; in fact, thiazolidinediones (TZDs) show the ability to contain tumor growth in vitro and in vivo models of lung cancer." (PMID 29966227, 2018). "Moreover, we explored whether PPARγ agonist efatutazone and the LXRα agonist T0901317exert similar synergistic effects on proliferation in lung cancer cells." (PMID 29573196, 2018). "Its involvement in adipocyte differentiation and glucose and lipid homeostasis is well-recognized, but accumulating evidence now suggests that PPARγ may also function as a tumor suppressor, inhibiting development of primary tumors and metastases in lung cancer and other malignancies." (PMID 27698657, 2016). "For example, along with sumoylation, PPARγ phosphorylation could play an important role in lung cancer pathogenesis as fibroblast growth factor (FGF) activated- or cyclin-dependent kinase 5 (CDK5) phosphorylation of PPARγ revealed pathologically or physiologically altered PPARγ signaling." (PMID 26244663, 2015). "Indeed, several clinical studies targeting PPARγ have been executed recently to treat advanced lung cancer patients since many preclinical lung cancer studies have proposed the anti-inflammatory function and therapeutic potential of PPARγ for treating lung cancer." (PMID 26244663, 2015). "In this article,we will review recent data, both from basic sciences experiments and fromclinical studies indicating that activation of the nuclear receptor peroxisomeproliferator-activated receptor γ (PPARγ) may represent a novel strategy for thetreatment and prevention of lung cancer." (PMID 18509496, 2008). "Thus, it has been postulated that PPARγ mRNA levels may serve as a prognostic marker in lung carcinoma in addition to playing important roles in lung carcinogenesis." (PMID 17597835, 2007). "While in liver cancer, PPARγ was identified as a TAM marker, the same transcription factor in lung cancer has been attributed to a distinct macrophage subpopulation." (PMID 40395129, 2025).
lung carcinoma (continued). "Cinobufagin inhibits M2 macrophage polarization by downregulating the PPARγ/MARCO axis, consequently suppressing lung cancer cell migration." (PMID 41459510, 2025). "Initially, using the lung cancer dataset, it was identified in VEGFC and proteins from the treatment datasets: RXRA, PPARG, and SMO." (PMID 40334012, 2025). "In lung cancer, Aquaporin 3 (AQP3) promotes M2 polarization and upregulates IL-6 secretion via the PPARγ/NF-κB signaling axis, thereby exacerbating glucose metabolic disorders through the IL-6R pathway." (PMID 41459510, 2025). "The pattern ‘CEGCKGFF’ appeared in 10% of lung cancer cases, specifically in the proteins RARB and VDR, and was also found in NR1I2 and PPARG within the treatment dataset." (PMID 40334012, 2025). "PPARγ can activate AMPK in adipose tissue.AMPK enhances PPARγ deacetylation, thermogenic proteins (UCP-1).Rosiglitazone increases AMPK and AKT in lung cancer models (Muscle Preservation)." (PMID 41476922, 2025). "In summary, ROB inhibited the proliferation, migration, invasion and EMT of lung cancer cells and activated the PPARγ/PTEN/Akt signaling pathway, as well as induced autophagy in lung cancer cells." (PMID 39450260, 2024). "These GO terms encompass six genes relevant to lung cancer found primarily in “Pathways in cancer” GO and partially overlapping with two other GOs: FLT3, FOXO1, CSF1R, RUNX1, PPARG, and TGFBR2." (PMID 39201328, 2024). "The western blot results shown that the expression of PPARγ and PTEN was higher and the expression of p-Akt/Akt was lower in lung cancer cells treated with ROB compared with control cells." (PMID 39450260, 2024). "Moreover, assessment of the activity levels of PPARγ may be useful as biomarkers for lung cancer." (PMID 37190124, 2023). "It has been shown that statins can trigger apoptosis in human lung cancer cells, and prevent cell proliferation and EMT in bladder cancer cells through a PPARγ-dependent pathway." (PMID 36902342, 2023). "In contrast, Src inhibition decreases PPARγ expression and subsequently reduces FABP4, which blocks cell survival in lung cancer cells." (PMID 35216267, 2022). "The expressions of C/EBPα and PPARγ were upregulated in several cell lines, and SREPB1, HIF-1α, PPARα, and PPARβ were more widely overexpressed in lung cancer cells." (PMID 36293388, 2022). "On the other hand, among the co-downregulated transcription factors in lung cancer, we focused on RUNX1, histone deacetylase 2 (HDAC2), and peroxisome proliferator-activated receptor gamma (PPARG)." (PMID 36142846, 2022). "In lung cancers, CBD acts up-regulating PPARγ levels directly and indirectly by increasing prostaglandin levels, which leads to a nuclear PPARγ accumulation and subsequent induction of apoptosis." (PMID 31979368, 2020). "PPARγ agonists also upregulate the expression of PTEN 39, resulting in inhibition of the PI3K-Akt signaling pathway in lung cancer." (PMID 32328200, 2020). "In lung cancer, it was determined that the expression of FABP4 can be induced by the transcriptional activity of PPARγ, mediating lipolysis and tumor growth suppression." (PMID 31803141, 2019). "On the contrary, PPARγ agonists were found to upregulate PTEN, subsequently inhibiting the PI3K-Akt signaling pathway in lung cancer cells." (PMID 30845932, 2019). "We first identified sumoylation of endogenous and exogenous PPARγ in lung cancer Calu6 cells and HEK 293 transfected with PPARγ, respectively." (PMID 29137280, 2017). "Consistent with the observation in the lung cancer panel, ORO experiment showed TZD induction of lipid droplet accumulation in a PPARγ sumoylation-dependent manner, which was observed only in HBEC-PPARγWT but not in HBEC-PPARγSUMO." (PMID 29137280, 2017). "This is of particular note because 15-LOX-1 expression and 13-S-HODE levels are suppressed in lung cancer cells and in other systems, sildenafil has been shown through PKG to regulate PPARγ." (PMID 27903966, 2017).
lung carcinoma (continued). "The peroxisome proliferator-activated receptor γ (PPARγ) and its agonists block TGF-β-induced EMT in lung cancer cells and suppress metastasis in recipient mice." (PMID 27430378, 2016). "Therefore, the ability to engage or otherwise control regulatory elements distinct from classic PPAR response element sites complicates the spectrum of genes that may be controlled by PPARγ and poses an important barrier to understanding the biological role of PPARγ in lung cancer." (PMID 22934105, 2012). "PPARg is expressed in human lung cancer cell lines (both SCLC and NSCLC), and its expression in lung cancer patients correlates with differentiation status and survival." (PMID 22701659, 2012). "This review summarizes investigations in therelationship between PPARγ,its ligands, and COX-2 and PGE2 in lung cancer." (PMID 18769553, 2008). "This article summarizes recent research on the relationship between (PPARγ), TZDs, and the COX-2/PGE2 pathways in lung cancer." (PMID 18769553, 2008). "These authors further demonstrated that transgenic miceover-expressing PPARγ exhibited reduced COX-2 in type II alveolar epithelialcells of lung, and those mice were protected against lung cancer development ina chemical carcinogenesis mouse model." (PMID 18769553, 2008). "Interestingly, PPARγ expression aligns with descriptions of SPP1+ macrophages as foamy cells, a feature reported in lung cancer TAMs expressing both TREM2 and SPP1, where they have been shown to promote cholesterol efflux, fuelling tumour cell metabolism." (PMID 40395129, 2025). "Compared with normal lung tissues, the expression of MMP3, MMP9, and PPARG was increased in lung cancer tissues, and the expression of ALOX5 and ICAM1 was decreased in lung cancer tissues, which was basically consistent with the analysis results in the GEPIA database." (PMID 39440769, 2025). "In addition, PPARγ agonists, prostaglandin J2 (PGJ2), ciglitazone, troglitazone, and GW1929 have been shown to inhibit the growth of lung carcinoma cells by upregulating p21 levels and reducing cyclin D1 expression." (PMID 41304753, 2025). "Moreover, troglitazone-induced PPARγ activation was shown to phosphorylate extracellular-signal-regulated kinase (ERK1/2), leading to mitochondrial-dependent apoptosis in NCI-H23 lung cancer cells." (PMID 41304753, 2025). "(2013) observed that CBD induces apoptosis in lung cancer cells by upregulating cyclooxygenase-2 (COX-2) and peroxisome proliferator-activated receptor gamma (PPAR-γ), resulting in apoptotic cell death via nuclear translocation of PPAR-γ." (PMID 40599866, 2025). "Lung cancer cell lines (A549 and H460), treated with CBD IC50 (3.47 and 2.80 μM), respectively, activated COX-2- and PPARγ-dependent apoptosis because the use of COX-2 (NS-398) and PPAR-γ (GW9662) inhibitors removed the cytotoxic and apoptotic effect of CBD." (PMID 40006844, 2025). "13-S-hydroxyoctadecadienoic acid (13(S)-HODE) and 15(S)-hydroxyeicosatetraenoic acid (15(S)-HETE), as endogenous ligands for PPARγ, were significantly reduced in NNK-induced lung cancer and could inhibit NSCLC when exogenously supplemented." (PMID 38397426, 2024). "Given the multiple functions of PPARγ activation in lung cancer, PPARγ agonists included thiazolidinediones and non-thiazolidinediones have been used as therapeutic agents to tackle lung cancer in preclinical and clinical studies." (PMID 38397426, 2024). "For instance, EGR1, JUN, PPARG, and RELA may have a beneficial effect in lung cancer, related to inhibition of tumor proliferation and metastasis, induction of apoptosis, and sensitization for chemotherapeutic drugs." (PMID 36969247, 2023). "Therefore, the combined use of PPARγ agonists and EGFR TKIs have recently been suggested for the treatment of lung cancer patients." (PMID 37190124, 2023). "This might help in establishing tumor markers for lung cancer based on the level of endogenous PPAR ligands and the activities of PPARγ or PPARα." (PMID 35631448, 2022).
lung carcinoma (continued). "In addition, the chemical activation of PPARγ increases fatty acid binding protein 4 (FABP4) expression, which is accompanied by increased levels of intracellular reactive oxygen species in lung cancer cells." (PMID 34775964, 2021). "Although, bavachinin-induced apoptosis in A549 lung cancer cells and G2/M cell cycle arrest in SCLC cells, through peroxisome proliferator-activated receptor γ (PPARγ)/reactive oxygen species (ROS) and the ATM/ATR signaling pathway, has been established, respectively." (PMID 34500594, 2021). "Our data indicated that PPARγ affected cell growth of lung cancer cells expressing LXRα and ABCA1, we attempted to examine whether PPARγ regulated the expression of LXRα and ABCA1." (PMID 29573196, 2018). "The inverse correlation between ALOX15B levels and lung cancer grade can be explained by the fact that 15(S)-HETE can bind and activate PPARγ, a nuclear transcription factor shown to inhibit the growth of human NSCLC cells as well as prevent smoking-induced lung cancer development in mice." (PMID 28704416, 2017). "Taken together, these data clearly suggest that, PPARγ disrupts REDOX balance by regulating cellular lipid metabolism which depletes NADPH by fatty acid synthesis and increases mitochondrial ROS from β-oxidation in lung cancer cells." (PMID 29137280, 2017). "Unlike PPARγ agonists, however, the clinical applicability of PPARα and PPARβ/δ ligands in lung cancer has not been assessed." (PMID 28316613, 2017). "Here, we found that ligand-mediated PPARγ activation induces intracellular lipid accumulation via uptake as well as biosynthesis, rather than mitochondrial β-oxidation in lung cancer." (PMID 29137280, 2017). "In addition, CCC also inhibited PPARγ mRNA expression in A549 lung cancer cells, indicating that CCC affected the expression of PPARγ in DMI-independent manner." (PMID 25181477, 2014). "PPARγ also interacts with and is activated byERK5 in order to inhibit (in conjunctionwith WNT signaling factors) the proliferation of lung cancer (NSCLC) cells andinflammation in endothelial cells upon flow (shear stress), indicative of aprotective function of ERK5-PPARγ cooperation." (PMID 18596912, 2008). "Generating such data could enable the developmentof a mechanistic model that could explain the inefficient response of PPARγ, inthe context of overexpression of the LOX/COX pathways, in lung cancer." (PMID 19277204, 2008). "Several studies have demonstrated that PPARγ activation can inhibit activation of NF-κB in NSCLC.While effects on HIF-1 have not been documented in lung cancer cells,PPARγ has been shown to inhibit HIF-1 in other systems." (PMID 18509496, 2008). "Thus,in lung cancer, PPARγ agonists appear toregulate COX-2 expression and affiliated protumorigenic cellular phenotypesthrough both PPARγ dependent andindependent means." (PMID 18769553, 2008). "Unlike our work, others have found that PPARγ activation not onlyinhibits lung-cancer cell growth, increases cell differentiation, andinduces cell-cycle arrest, but that it also induces apoptosis." (PMID 17389773, 2007). "Non-TZD PPARγ agonists have also been explored the potential of the treatment of lung cancer." (PMID 38397426, 2024). "In addition, PPARγ agonists, including ciglitazone, PPZ023, and CB13, could function as a radiosensitizer in radioresistance-related lung cancer through inducing ROS generation or ER stress." (PMID 38397426, 2024). "Furthermore, pharmacological stimulation of PPARγ leads to an elevation in the production of fatty acid binding protein 4 (FABP4), which is followed by an increase in the amount of reactive oxygen species in lung cancer cells." (PMID 38933330, 2024). "In one study, human lung cancer cell lines were shown to express PPARγ but not PPARα." (PMID 35631448, 2022).
lung carcinoma (continued). "Further biochemical analysis revealed that PPARγ-mediated lipid synthesis depletes nicotinamide adenine dinucleotide phosphate (NADPH), consequently resulting in increased mitochondrial reactive oxygen species (ROS) level that subsequently disrupted REDOX balance in lung cancer." (PMID 29137280, 2017). "Although recently a clinical retrospective database analysis had reported that PPARγ agonists (thiazolidinediones) reduced lung cancer risk in diabetic patients, there was no rational explanation and the mechanistic data explaining PPARγ action in lung cancer are controversial." (PMID 21664456, 2011). "However, the role of PPARγ activation by systemic administration of TZDs in regulating tumor progression and metastasis of lung cancer has not been well studied." (PMID 22145026, 2011). "Furthermore, this agent inhibits lung cancer cell growth and its antiproliferative action does not occurs via PPARγ activation." (PMID 19737384, 2009). "Our group has shown that PPARγ agonists including ciglitazone, troglitazone,and GW1929 induce the expression of death receptor 5 (DR5) including increasingthe cell surface distribution of DR5, reducing the levels of c-FLIP, andenhancing TRAIL-induced apoptosis in human lung cancer cells." (PMID 18615184, 2008). "Furthermore, M.SssI maps and EMSA experiments suggested that PPARg might be binding to the Cadm1 promoter in a lung cancer cell line (A2C12), but not in normal lung." (PMID 22701659, 2012). "This is the first report of PPARγ activity-dependent PTEN induction in macrophages exposed to apoptotic, but not necrotic, lung cancer cells." (PMID 30842627, 2019). "Taken together, this suggests that ligand-induced PPARγ sumoylation is specifically involved in the suppression of inflammatory COX2 and TNFα signaling pathways, but not the iNOS pathway, in lung cancer pathogenesis." (PMID 26244663, 2015). "EMSA results suggested that PPARg bind in vitro to the Cadm1 promoter with nuclear extracts from the lung cancer cell line (A2C12), but not in normal lung, and could play a role in lung cancer." (PMID 22701659, 2012).